MMP7 (matrix metallopeptidase 7)
Diseases named in the same sentence as MMP7 in open-access papers (continued):
Sharing a sentence is not in itself a finding about the gene and the disease.
tumor (continued). "To validate the DASL observations, we performed quantitative RT-PCR on the representative upregulated genes, and observed that the expression of mRNAs, including MMP7, NOTCH1, FZD7, were significantly higher in TN tumor samples than in non-TN tumor samples." (PMID 24143235, 2013). "The mRNA levels for several critical components of the pathway (BIRC5, CD44, FZD7, c-MET, MMP7, c-MYC, NOTCH1, PPARD, and VEGF) were significantly increased (DASL signal intensity) in TN tumor samples as compared to non-TN tumor samples." (PMID 24143235, 2013). "Moreover, MMP7, MMP13, and MMP10 were significantly upregulated in metastatic tumour samples compared with nonmetastatic tumour samples." (PMID 31996191, 2020). "The value of TIMP1, MMP7, and TSP2 as circulating biomarkers was corroborated in PDAC‐PDX‐bearing mice where the plasma levels of these molecules reflected the high levels found in the corresponding patient's plasma (data not shown) and correlated with tumor burden over time." (PMID 29941541, 2018).
cancer (421 papers, 2002 to 2026). A tumor composed of atypical neoplastic, often pleomorphic cells that invade other tissues. "MMP7+ cancer cells, enriched in genes associated with the humoral immune response, were abundant in sensitive cases." (PMID 41016944, 2025). "For example, MMP-7 has been linked to cancer cell migration and immune modulation, while MMP-12 is involved in inflammation and has roles in certain cancers." (PMID 40265458, 2025). "MMP7, recognized for its role in extracellular matrix remodeling, has been implicated in the pathogenesis of several cancers, including AML." (PMID 40790216, 2025). "In our opinion, an activated immune microenvironment can be associated with the heterogeneity of cancer cells (e.g., MMP7+ cancer cells)." (PMID 41016944, 2025). "In the Indian population, MMP7 (-181A>G) polymorphism was previously evaluated to probe its association with various other cancers." (PMID 38638796, 2024). "High levels of MMP7 are associated with shorter survival in cancer patients, while the prognostic role of MMP9 is controversial." (PMID 35928876, 2022). "Significant positive correlations between MMP7 expression and cancer-associated fibroblasts (CAFs) have been demonstrated in most TCGA cancers." (PMID 35785154, 2022). "The variant 181A ⟶ G (rs11568818), which is found in the MMP-7 promoter region, is known to modulate the expression of genes and proteins and has been studied in various disease conditions, including cancers." (PMID 35496040, 2022). "MMP7 is implicated in the aggression of cancer cells, thus is also presumed to play a vital role in the drug resistance of cancer cells." (PMID 32761892, 2022). "MMP-7 also exhibits proteolytic activity on components of the extracellular matrix, is often overexpressed in human cancer tissues and is associated with cancer progression." (PMID 34502094, 2021). "Our aim was to generate a unique function blocking monoclonal antibody against one such cancer-associated enzyme, matrix metalloproteinase 7 (MMP-7)." (PMID 33918254, 2021). "GSM-192 is a valuable therapeutic, diagnostic and research tool to validate MMP-7 as a suitable drug target in cancer and inflammation." (PMID 33918254, 2021). "Matrix metalloproteinase 7 (MMP7), as the smallest member of the matrix metalloproteinase family, has been verified to be implicated in cancer progression, especially metastasis." (PMID 31937294, 2020). "A number of reports have suggested that polymorphisms in MMP3 and MMP7 are important risk factor for therapeutic resistance in cancer." (PMID 35047986, 2020). "This suggests a potential field effect for the development of cancer and thus associated risk-factors, highlighting the potential utility of MMP7 as a biomarker, as previously suggested for other diseases." (PMID 31882975, 2019). "The subgroup analysis by cancer type,showed that there was significant association between the MMP-7 -181A>Gpolymorphism and increased risk of GC in overall estimations, but not with CRC." (PMID 31644669, 2019). "A meta-analysis of 24 studies revealed the association of rs11568818 in MMP-7 with cancer risk differed among ethnicities." (PMID 30036379, 2018). "In particular, MMP7 is associated with highly invasive phenotypes that lead to poor prognoses in cancer patients." (PMID 28757546, 2017). "MMP7, one of the secreted proteolytic enzymes, is associated with invasion and metastasis of cancers including PCa." (PMID 27356744, 2016). "MMP7 is associated with cell proliferation, mobility and cancer progression, yet the mechanism on MMP7 elevation in cancers is poorly understood." (PMID 27356744, 2016). "In the context of cancer biology, only a limited number of Kaiso target genes have been identified thus far, including the matrix metalloproteinase matrilysin (MMP7), metastasis-associated gene 2 (MTA2), cyclin D1 (CCND1) and Wnt11 (WNT11)." (PMID 25713299, 2015).
cancer (continued). "Looking for downstream target genes, we demonstrate miR-126&126* capabilities to directly regulate a disintegrin and metalloprotease domain 9 (ADAM9) and metalloprotease 7 (MMP7), whose aberrant expressions have been associated with a wide variety of cancers." (PMID 23437250, 2013). "MMP7, also known as matrilysin, is a secreted protein implicated in a broad range of extracellular matrix substrates destruction in various cancers." (PMID 24325363, 2013). "In the multiple logistic regression model adjusted for age, gender and smoking habits, a unit increase in log DNA and log MMP-7 was associated with a 2.21- and 15.14-fold increase in cancer risk, respectively." (PMID 24336111, 2013). "SDC2 serves as a docking receptor for matrix metalloproteinase (MMP)-7 in cancer cells, an enzyme implicated in the pathogenesis of fibrosis." (PMID 22900087, 2012). "Four studies evaluated MMP2 (−1306) C/T and its association with cancer metastasis, and only three evaluated the association between MMP7 (−181) A/G and metastasis." (PMID 22348060, 2012). "MMP7 encodes a proteolytic enzyme known to facilitate cancer cell mobility and invasion." (PMID 41335396, 2025). "This may also indirectly confirm the theory that high expression and concentrations of MMP-10 may be associated with and correspond to, just like MMP-7, an increase in cancer progression." (PMID 41462922, 2025). "MMP7 is known to be overexpressed in many types of cancer and is associated with poor prognosis." (PMID 39187937, 2024). "All these observations suggest that the MMP7 (-181A>G) genetic polymorphism may contribute to the susceptibility of cancer." (PMID 38638796, 2024). "We identified the overexpression of vascular endothelial growth factor-α (VEGFA)/β-catenin/matrix metalloproteinase (MMP)-7/Cluster of Differentiation 44 (CD44) in CRC to be associated with cancer progression, stemness, resistance to therapy, metastasis, and poor clinical outcomes." (PMID 36672201, 2023). "MMP-7 expression is associated with clinical characteristics of cancer patients." (PMID 38203373, 2023). "In addition, MMP-7 is associated with an aggressive cancer phenotype and poor prognosis in patients with gastric cancer." (PMID 37513440, 2023). "Moreover, a specific polymorphism of MMP-7 (rs11568818) modulates protein expression and possibly affects cancer progression." (PMID 35496040, 2022). "We selected CDH3, LEF1, and MMP7 as candidate biomarkers to construct a back propagation neural network model from hub genes, which may be helpful for the early diagnosis of cancer through the high-risk early warning range." (PMID 34485109, 2021). "A panel of MMPs was analyzed in serum from PC patients—specifically, MMP-1, MMP-3, MMP-7, MMP-9, MMP-10, and MMP-12 were higher in cancer patients compared with healthy donors, showing good diagnostic accuracy, of which MMP-7 and MMP-12 achieved perfect discrimination." (PMID 30678058, 2019). "Under pathological conditions, MMP7 overexpression has been associated with cancer-cell invasion and metastasis, and MMP7 regulates cancer-associated processes, such as the inhibition of apoptosis, the degradation of cell-cell contact and cellular proliferation." (PMID 29484116, 2018). "While this study focused on MMP-7 staining amount in relation to perlecan, other MMPs and even other classes of cancer-associated proteases (i.e. membrane type 1 and 2 MMP) almost certainly contribute to the proteolysis of perlecan during cancer invasion of tissue." (PMID 26862737, 2016). "In addition, three putative targets (MMP1, MMP2, and MMP7) of marketing anti-cancer drugs were reported to be associated with NSCLC." (PMID 24429698, 2014). "Similarly, analysis of MMP-7 plasma level in 135 patients with localized bladder cancer (?T1) confirmed the significant association of MMP-7 level with cancer-related death." (PMID 25984271, 2014).
cancer (continued). "The Kaiso protein, like other members of the subfamily POZ-ZF, has been implicated in cancer development process when it has been found that Kaiso inhibits activation mediated by β-catenin of the Mmp7 gene (also known as matrilysin), which is well known for metastatic spread." (PMID 22709531, 2012). "The MMP7-expressing cancer cells frequently co-expressed MMP1, MMP14, and several Wnt-related genes, consistent with a cancer cell type at high risk of malignancy and metastasis." (PMID 42079046, 2026). "Epithelial-rich areas showed subregions of MMP7-expressing cancer cells, including areas where cancer cell and myeloid MMP expression overlap." (PMID 42079046, 2026). "Our single-cell multiomic analyses reveal that the pdECM activates transcriptional programs involving the AP-1 complex, with downstream targets like MMP7 playing key roles in promoting cancer cell invasion." (PMID 40954257, 2025). "Compared with the resistant cases, the sensitive cases presented a significantly lower proportion of cancer cells expressing CDK1 (P = 0.019) and a trend toward a greater proportion of cancer cells expressing MMP7 (P = 0.067)." (PMID 41016944, 2025). "Consistently with its functional role and further reinforcing its association with MSLN, elevated MMP-7 expression has been reported across several MSLN-positive malignancies, including pancreatic, breast, colorectal, ovarian, and NSCL cancers." (PMID 41335396, 2025). "Another piece of evidence supporting the relationship between MSLN and MMP-7 and their involvement in cancer metastasis comes from a study conducted on NSCLC." (PMID 41335396, 2025). "This pattern coincided with the upregulation of key markers associated with cancer stemness (CD133, CD44) and metastasis/invasion (MMP7, CD74), highlighting FXYD5 as a potential driver of malignant progression." (PMID 41457101, 2025). "They confirmed that MMP7 expression had different effects on immune cell infiltration in the TME according to cancer type." (PMID 40900789, 2025). "Silencing MMP7 in CC cell lines has been shown to decrease proliferation, migration, and invasion, further reinforcing its role in cancer progression." (PMID 40599331, 2025). "MMP7 has been recognized as an oncogenic protein that contributes to the tumorigenesis, infiltration, and metastasis of different cancers." (PMID 40768895, 2025). "MMP-26 also belongs to the matrilysin group and, like MMP-7, is an important enzyme in the progression of cancer." (PMID 40565125, 2025). "The proportions of cancer cells_CDK1 and cancer cells_MMP7 were similar between the “PFS < 6 m” and “progression” groups." (PMID 41016944, 2025). "These Q NPs effectively inhibited cell growth of liver cancer and colony formation by upregulating p27 and downregulating c-Myc, cyclinD1, cyclin-dependent kinase 1 (CDK1), matrix metallopeptidase 7, and β-catenin within the cancer cells." (PMID 40830621, 2025). "In contrast, advanced LCRC is characterized by MMP7+ cancer cells expressing ECM remodeling genes and possess significantly higher metastatic potential." (PMID 41450739, 2025). "MMP7 promotes cancer progression by degrading the extracellular matrix (ECM), enhancing epithelial-mesenchymal transition (EMT), supporting angiogenesis, and modulating the immune response, all of which contribute to increased metastasis." (PMID 40168262, 2025). "Emodin, another selected compound based on in silico experiments, inhibits cancer growth by suppressing the expression of MMP7, MMP9, VEGF, EMT, N-cadherin, b-catenin, and Snail based on the literature." (PMID 38918540, 2024).
cancer (continued). "Hereon, our research revealed that PACAP38 downregulated the crucial effector (β-catenin), nuclear transcription factors (LEF1, TCF1/TCF7), and downstream target genes (MMP7, cJUN, c-myc and CD44) associated with the Wnt/β-catenin signaling in cancer cells." (PMID 39619607, 2024). "The relative expression for three of them were validated by q-PCR as MMP-7 was upregulated in cancer cells." (PMID 38097858, 2024). "MMP-7 degrades extracellular matrix components, which contributes to tissue remodeling and cancer spread." (PMID 39596310, 2024). "Matrix metalloproteinases (MMPs), particularly MMP13, MMP1, and MMP7, are known to play a significant role in cancer progression." (PMID 38707175, 2024). "IL-24 facilitates cSCC invasion by increasing focal MMP-7 expression, and MMP-7 promotes cancer cell proliferation, migration, and invasion." (PMID 36793738, 2023). "MMP-7 is abundantly expressed in many types of cancer tumors, including breast, colon, oesophageal, pancreatic, and lung cancer." (PMID 37513440, 2023). "As a consequence, via the upregulation of tissue inhibitor of metallopeptidase-1 (TIMP1), the expression of matrix metallopeptidase-7 (MMP-7) is hindered, preventing the invasion of cancer cells." (PMID 35682652, 2022). "This pan-cancer analysis provides a clear panorama for the tumorigenic roles of MMP7 across different cancer types." (PMID 35785154, 2022). "The exosome-activated mCAFs upregulate the activity of genes for MMP-1, MMP-2, MMP-7, MMP-8, MMP-13 and MMP-14 that are associated with cancer growth and progression." (PMID 34837514, 2022). "Other evidence regarding elevated MMP-7 levels in drug-resistant cancers have shown the involvement of MMP-7 and Fas interaction in the acquisition of resistance towards chemotherapeutic drugs." (PMID 35586209, 2022). "MMP-7 mediated the conversion of E-cad into a soluble form, allowing cancer cells to dislodge from the primary tumor during the early stage of metastasis." (PMID 36250005, 2022). "There were three variants remarkably related to cancer risk, including MMP-2 rs243865, MMP-7 rs11568818, and MMP-9 rs3918242." (PMID 35574300, 2022). "Some of the differentially expressed genes included cancer progression factors, such as Tff1 (trefoil factor 1), Anxa10 (annexin a10), Gnai1 (G protein subunit alpha i1), Areg (amphiregulin), and Mmp7 (matrix metalloproteinase 7)." (PMID 35703180, 2022). "Previous in vitro cancer research has highlighted varied effects of MMPs on DPC-proliferation with MMP7 inhibiting cell proliferation and MMP9-inhibition increasing proliferation of satellite cells in dystrophic-muscle." (PMID 35531096, 2022). "Recently, MMP7 upregulation has been confirmed in various human cancer types, including lung, melanoma, esophagus, gallbladder, stomach, pancreas, colon, bladder, and other malignancies." (PMID 35785154, 2022). "Its high cancer-killing selectivity was ascribed to the specific recognition and binding of RGD segment to cancer membranes and the cleavage of PLGLA segment by the cancer-overexpressed matrix metalloproteinase-7 (MMP7)." (PMID 36012300, 2022). "MMP7 is also called matrilysin, which plays the role of a metastatic factor by promoting the migration and invasion of cancer cells; overexpression of MMP7 was found in HCC." (PMID 35938176, 2022). "Several aptamer-based probes have been developed using upregulated membrane-bound or membrane-associated proteolytic enzymes, such as MMP-2, MMp-7, and MMP-9, for cancer diagnosis." (PMID 36431072, 2022). "Further, they demonstrated a direct interaction between the hybrids and MMP7 molecules, suggesting the modulation of MMP7 catalytic activity, hence preventing cancer cell progression." (PMID 36015440, 2022).